EPHA2 (EPH receptor A2)
Diseases named in the same sentence as EPHA2 in open-access papers (continued):
Sharing a sentence is not in itself a finding about the gene and the disease.
leukemia (continued). "In particular, EphA2 was expressed at different levels in individual leukemic samples but the significant expression in a proportion of clinical samples bearing the 11q23 chromosomal (MLL) re-arrangement, suggested that EphA2 might be a therapeutic target in human MLL-driven leukemia." (PMID 26083390, 2015). "However, expression of EphA2 in leukemias initiated by MLL-AF9 suggested that this protein might be a possible therapy target in this type of leukemia." (PMID 26083390, 2015). "The GFP+ leukemic cells from both EphA2 knockout and wild type MLL-AF9 mice induced leukemia with similar disease latencies." (PMID 26083390, 2015). "We have also examined the expression of EphA2 in the mouse model of leukemia and observed that MLL-AF9 induced murine leukemia have elevated EphA2 expression." (PMID 26083390, 2015). "Comparative studies using EphA2-negative MLL-AF9 leukemias derived from EphA2-knockout animals showed that there was no detectable functional role for EphA2 in the initiation or progression of the leukemic process." (PMID 26083390, 2015). "There are also reports of EphA2 expression in many different types of malignancies including leukemia, however there is a lack of knowledge in understanding the role of EphA2 in hematopoiesis and leukemogenesis." (PMID 26083390, 2015). "The results from this transplantation showed that lack of EphA2 expression in the donor mice was dispensable for the generation of leukemia." (PMID 26083390, 2015). "Most of the protein hits could be identified in blood samples according to the HPA database; two of them, namely DPEP1 and SOST, were classified by HPA as upregulated in BC; and five of them were found to be upregulated in leukemia and myeloma: SOST, TXNRD1, PKLR, EPHA2, PLIN3." (PMID 38791048, 2024). "A possible explanation for lack of effect of EphA2 deletion in MLL-AF9 leukemia is that other Eph proteins with overlapping ephrin-binding affinities, such as EphA7 that was reported previously on MLL-AF9 leukemias, might show a compensatory increase in expression." (PMID 26083390, 2015). "Whilst EphA2 expression was not critical for the leukemic process, a significant level was detected on most cases of MLL-AF9 murine leukemia indicating that this protein might be a potential radiolabeled therapeutic target in the treatment of MLL-AF9 leukemias." (PMID 26083390, 2015).
lung adenocarcinoma (9 papers, 2015 to 2025). A carcinoma that arises from the lung and is characterized by the presence of malignant glandular epithelial cells. "HeLa cells, human breast adenocarcinoma (MDA-MB-231) cells, human lung adenocarcinoma and squamous cell carcinoma biopsy samples, and human vascular smooth muscle cells stained for EphA2-pS897 also revealed a diffuse intracellular pattern." (PMID 39466050, 2024). "Furthermore, knockdown of EphB4 has been reported to suppress the cell proliferation of lung adenocarcinoma cell lines, and knockdown of EphA2 has been reported to improve gefitinib sensitivity in gefitinib-resistant lung adenocarcinoma cell lines." (PMID 34445227, 2021). "The clinical relevance of VM is underscored by the development of “VM-scores” based on EPHA2, LAMC2, and LOXL2 genes, which serve as independent prognostic markers in lung adenocarcinoma." (PMID 40786517, 2025). "Correlation analysis using RNA sequencing data from the TCGA further showed that TGFB2 correlated significantly with EPHA2 expression in lung adenocarcinoma samples, though other myeloid markers and immunosuppressive proteins were not significantly correlated with EPHA2 expression." (PMID 40867322, 2025). "However, CAR-T cells against LSCC have never been reported although CAR T cells that target FAP, EphA2 and EGFR have been developed for the treatment of lung adenocarcinoma." (PMID 26684028, 2016).
pancreatic ductal adenocarcinoma (9 papers, 2014 to 2025). An infiltrating adenocarcinoma that arises from the epithelial cells of the pancreas. "Similarly, in pancreatic ductal adenocarcinoma, EphA2 is associated with a poor prognosis and is considered a sensitive diagnostic biomarker." (PMID 39839790, 2024). "Patients with intraductal papillary mucinous neoplasm (IPMN), a precancerous pancreatic ductal carcinoma lesion, also show high serum EphA2 levels, which are associated with an increase in pancreatic duct size and the development of pancreatic ductal carcinoma in some cases." (PMID 37712876, 2023). "Thus, serum EphA2-NF could be a diagnostic biomarker for very early-stage pancreatic ductal carcinoma and pancreatic ductal carcinoma development from high-risk IPMN and as a prognostic biomarker after chemotherapy with GnP." (PMID 37712876, 2023). "Cleavage of erythropoietin-producing hepatocellular ephrin receptor A2 (EphA2) triggers malignant progression and yields an N-terminal fragment (EphA2-NF) detectable in sera from patients with pancreatic ductal carcinoma." (PMID 37712876, 2023). "We established a quantitative automated chemiluminescence immunoassay for EphA2-NF and evaluated serum EphA2-NF levels as a biomarker to diagnose pancreatic ductal carcinoma in the test and validation cohorts." (PMID 37712876, 2023). "Among patients receiving standard chemotherapy for pancreatic ductal carcinoma [gemcitabine plus nab-paclitaxel (GnP)], the median survival time of patients with elevated serum EphA2-NF was half that of patients with values below the cutoff." (PMID 37712876, 2023). "The EphA2-NF value was elevated (above the cutoff: mean ± SD) in more than half of the patients with stage I/II pancreatic ductal carcinoma." (PMID 37712876, 2023). "Meanwhile in pancreatic ductal adenocarcinoma, EphA2 expression negatively correlates with T cell infiltration, leading to discovery of an immunosuppressive EphA2/TGFβ/COX-2 signalling axis." (PMID 36175961, 2022). "Normal human pancreatic tissue, chronic pancreatitis tissue, and human pancreatic ductal adenocarcinoma tissue were also probed for EphA2 expression using a rabbit anti-EphA2 (ab78002, abcam, 1/200)." (PMID 26959746, 2016). "IHC showed loss of EphA2-NF staining in IPMN with pancreatic ductal carcinoma, but not in the normal epithelium or IPMN without pancreatic ductal carcinoma, regardless of the histologic grade." (PMID 37712876, 2023). "In addition, in human pancreatic ductal adenocarcinoma, the EphA2 antibody clearly stained cancerous ducts and fibroblast cells within stroma." (PMID 26959746, 2016). "Furthermore, it has been reported that the overexpression of EPHA2 upregulates the expression of MMP-2 in Capan2 pancreatic ductal adenocarcinoma cells." (PMID 24932309, 2014). "EphA2 N-terminus deletion is involved in pancreatic ductal carcinoma development from high-risk IPMN and EphA2-NF produced by cleavage can be used as a serum biomarker to diagnose pancreatic ductal carcinoma and predict pancreatic ductal carcinoma development from high-risk IPMN." (PMID 37712876, 2023).
breast tumor (8 papers, 2016 to 2024). "EphA2 has been implicated in breast tumors and resistance of tumors to targeted therapies." (PMID 34717732, 2021). "In the EMT6 breast tumor model, the deployment of EphA2-targeted liposomal paclitaxel, termed “EphA2-il-dtxp”, in conjunction with the PD-L1 blockade, elicited a significant tumor response in vivo." (PMID 38612592, 2024). "Of note, the receptor tyrosine kinase EPHA2 has been involved in breast tumor initiation and metastatic progression of HER2+ BC by amplifying HER2 signalling." (PMID 33842315, 2021). "Together, these data suggest that elevated EphA2 expression in breast tumor cells promotes osteolytic disease in bone metastasis, at least in part, by upregulating IL‐6, which in turn enhances osteoclast differentiation to facilitate osteolysis." (PMID 33869989, 2021). "Together, these results indicate that the specific interaction between Anks1a and EphA2 is important for breast tumour growth in MMTV-Neu mouse model." (PMID 27619642, 2016). "This EphA2-mediated amplification of ErbB2 signalling contributes to breast tumour initiation and metastasis in mouse mammary tumour virus (MMTV)-ErbB2/Neu transgenic mice." (PMID 27619642, 2016). "Discrepancies in EPHA2 expression may also result from the inclusion of both invasive and noninvasive breast tumors in the TCGA database." (PMID 33977106, 2021).
endometrial cancer (8 papers, 2013 to 2024). Primary or metastatic malignant neoplasm involving the endometrium (mucous membrane that lines the endometrial cavity). "Mounting evidence has demonstrated the role of EphA2 in tumor growth and metastasis; further, EphA2 overexpression is associated with poor prognosis in several cancers, including endometrial cancer." (PMID 38279277, 2024). "EphA2, a receptor tyrosine kinase, is overexpressed by various cancers including endometrial cancer and is associated with poor clinical outcomes." (PMID 38279277, 2024). "Moreover, high expression of EphA2 was found in endometrial carcinoma and was significantly associated with adverse patient outcome." (PMID 34691070, 2021). "In this study, we identified and validated panobinostat as a synergistic partner to EphA2-targeted therapy for endometrial cancer." (PMID 38279277, 2024). "Previously, we demonstrated a synergistic interaction between EphA2- and Wee1-targeted therapies in endometrial cancer models through high-throughput chemical screens, which served as a platform for this study." (PMID 38279277, 2024). "Together, our results highlight EphA2 and histone deacetylase as promising therapeutic targets for endometrial cancer." (PMID 38279277, 2024). "For in vitro studies, we chose two endometrial cancer cell lines with high expression of EphA2 (Ishikawa and Hec1A)." (PMID 38279277, 2024). "Here, we identified a synergistic partner to EphA2-targeted therapy in endometrial cancer, namely, the HDAC (histone deacetylase) inhibitor panobinostat (LBH589)." (PMID 38279277, 2024). "In conclusion, our preclinical findings indicate that Wee1 inhibition can enhance the response to EphA2-targeted therapeutics in endometrial cancer; this strategy thus warrants further development." (PMID 36835335, 2023). "In this study, we sought to identify novel agents for combination with EphA2-targeted therapy in endometrial cancer." (PMID 36835335, 2023). "Next, we analyzed the synergism of EphA2 and Wee1 inhibition in two endometrial cancer cell lines (Hec1A and Ishikawa) known to have high expression levels of EphA2." (PMID 36835335, 2023). "To explore the effect of EPHA2 on endometrial cancer growth, we used the specific EPHA2 inhibitor ALW-II-41-27." (PMID 37057290, 2023). "In conclusion, EphA2- and Wee1-targeted therapies show synergistic interaction in endometrial cancer in both in vitro and in vivo experiments." (PMID 36835335, 2023). "In the present study, we identified the Wee1 kinase inhibitor, MK1775, as a synergistic partner to EphA2-targeted therapy in endometrial cancer cells." (PMID 36835335, 2023). "EphA2 tyrosine kinase is upregulated in many cancers and correlated with poor survival of patients, including those with endometrial cancer." (PMID 36835335, 2023). "In order to elucidate possible mechanisms involved in γδ T-cell cytotoxicity, we chose the EphA2 as it is often overexpressed in many cancers including endometrial carcinomas and also ranked 25th of cancer antigens prioritized for translational research." (PMID 34691070, 2021). "Thus, the combination of EphA2 and HDAC inhibition in endometrial cancer likely causes DNA damage, increased apoptosis, decreased clonogenic survival, and downregulation of the Axl-PI3K-AKT-mTOR pathway." (PMID 38279277, 2024). "To test our hypothesis, we examined the antitumor effects of an EphA2 inhibitor and panobinostat, as individual agents and in combination, in mouse models of endometrial cancer." (PMID 38279277, 2024). "To test our hypothesis that Wee1 inhibition sensitizes cells to EphA2-targeted therapy, we examined the anti-tumor effects of both agents in endometrial cancer mouse models and evaluated potential mechanisms of synergy." (PMID 36835335, 2023). "The combination of cell cycle checkpoint inhibitors and EphA2-targeted therapy may have utility in the treatment of endometrial cancer and warrants further investigation." (PMID 36835335, 2023).
endometrial cancer (continued). "The tyrosine kinase EphA2 is often overexpressed in cancer including endometrial carcinoma." (PMID 34691070, 2021). "Collectively, our results reveal a novel synergistic interaction between EphA2- and HDAC-targeted therapies in endometrial cancer." (PMID 38279277, 2024). "Here, we demonstrated the synergy and therapeutic potential of EphA2 and HDAC inhibition in endometrial cancer." (PMID 38279277, 2024). "The combination of EphA2 and HDAC inhibitors triggered DNA damage and inhibited the survival of endometrial cancer cells." (PMID 38279277, 2024). "We hypothesized that combined EphA2 and HDAC inhibition leads to synergistic endometrial cancer cell death." (PMID 38279277, 2024). "However, rational combinations with EphA2-targeted therapy are not yet known; therefore, we aimed to identify novel therapeutic combinations through high-throughput chemical screens for use in endometrial cancer." (PMID 36835335, 2023).
neuroblastoma (8 papers, 2014 to 2025). Neuroblastoma (NB) is the most common solid, extracranial childhood tumor. "Significantly, EPHA2 expression decreased after pharmaceutical treatment with doxorubicin, indicating its potential as a biomarker for drug responsiveness in neuroblastoma." (PMID 38612645, 2024). "Gene expression analysis via real time PCR (RT-PCR) conducted a few years later revealed variations in the EPHA2 expression levels among different neuroblastoma cell lines." (PMID 38612645, 2024). "As for neuroblastoma, low EPHA2 expression can discriminate the N-type from the S-type, which is characterized by high EPHA2 expression, while low EPHB4 levels are typical in embryonal rhabdomyosarcoma." (PMID 38612645, 2024). "The EPHA2 inhibitor ALW II-41-27 and the multitarget inhibitor dasatinib showed MES-specific activity across a panel of parental neuroblastoma cell lines." (PMID 39825754, 2025). "In addition, S(+)-ibuprofen enhanced the expression of some favorable neuroblastoma genes (EPHB6, CD44) and genes involved in growth suppression and differentiation (EGR1, EPHA2, NRG1 and SEL1L)." (PMID 24173829, 2014).
squamous cell carcinoma (8 papers, 2013 to 2025). A carcinoma arising from squamous epithelial cells. "One of these, EPHA2, is overexpressed in squamous cell carcinoma of oral tongue and was also protruding in our mutational analysis." (PMID 27596625, 2016).
age (7 papers, 2008 to 2021). A temporal measurement of the time period elapsed since an identifiable point in the life cycle of an organism. "Evidences have identified the correlation of 8-oxoguanine DNA glycosylase-1 (OGG1) and eph-receptor tyrosine kinase-type A2 (EPHA2) polymorphisms in age-related cataract (ARC) risk." (PMID 27681698, 2016). "Our previous study showed that a synonymous polymorphism within EPHA2 gene, named rs3754334, is associated with the risk of age-related cataract." (PMID 26664742, 2015). "Importantly, the missense mutations in EPHA2 associated with age-related cataract abolished the EPHA2-mediated enhancement of antioxidative capacity, suggesting the loss of function in both polymorphisms." (PMID 26664742, 2015).
atherosclerosis (7 papers, 2018 to 2023). A disease characterized by the build-up of fatty material and calcium deposition in the arterial wall resulting in partial or complete occlusion of the arterial lumen. "Although multiple SNPs in EphA2 are most commonly linked with congenital cataracts, the EphA2 gene locus is associated with premature myocardial infarction in humans and susceptibility to atherosclerosis in mice." (PMID 30283356, 2018). "Since deletion of EphA2 reduces inflammation and fibrosis associated with atherosclerosis, the development of a drug targeting EphA2 is an attractive option in treating cardiovascular disease." (PMID 30283356, 2018). "In an apolipoprotein E knockout murine atherosclerosis model, the knockdown of EPHA2 using adenovirus-carrying short hairpin RNA resulted in the attenuation of atherosclerotic lesion development." (PMID 32887275, 2020). "Taken together, we believe that EphA2 might be a crucial player in the initiation of the atherosclerosis process, specifically the recruitment of leukocytes to sites of inflammation." (PMID 33510642, 2020).
congenital cataracts (7 papers, 2010 to 2024). "A role for Ephrin signaling in eye development is also emerging: dominant mutations in EPHA2 cause isolated congenital cataracts, and its ligand EFNA5 is important for normal lens development." (PMID 36830662, 2023). "In this paper, we report two pathogenic EPHA2 variants in unrelated families presenting with bilateral microphthalmia and congenital cataracts." (PMID 33671840, 2021). "Both of these variants are known to disrupt EPHA2 function and have been previously reported to cause isolated congenital cataracts." (PMID 33671840, 2021). "Taken together, these results strongly suggest that mutation in EPHA2 is responsible for recessive congenital cataracts in the Pakistani family." (PMID 20361013, 2010). "Here, we report mutations in EPHA2 associated with autosomal recessive congenital cataracts in a consanguineous Pakistani family." (PMID 20361013, 2010). "Many human mutations in EphA2 are associated with age-related and congenital cataracts." (PMID 39466050, 2024). "In this study, we identified through next-generation sequencing (NGS) autosomal dominant EPHA2 variants segregating congenital cataracts and bilateral microphthalmia in two unrelated families: (i) missense variant c.1751C>T, p.(Pro584Leu) and (ii) splicing variant c.2826-9G>A." (PMID 33671840, 2021). "Cat-Map reports 22 pathogenic EPHA2 variants associated with congenital cataracts, variable microcornea, and lenticonus, but no previous association with microphthalmia (small, underdeveloped eye, ≥2 standard deviations below normal axial length)." (PMID 33671840, 2021).
nuclear cataract (7 papers, 2008 to 2021). A cataract (disease) that involves the lens nucleus. "Two probands who had nuclear cataracts plus microphthalmia and microcornea had a mutation in EPHA2; one of them was considered as likely pathogenic (Family 20)." (PMID 33923544, 2021). "Since the loss of EphA2 leads to mild nuclear cataracts, we examined whether changes in GJ coupling could be contributing to cataractogenesis." (PMID 34899394, 2021). "Since mild nuclear cataracts are often present in EphA2–/– lenses, we evaluated the localization of Cx46, Cx50, and Aqp0 by performing immunostaining in 6-week-old control, ephrin-A5–/– and EphA2–/– lens frozen sections." (PMID 34899394, 2021). "In EphA2 knockout (–/– or KO) mouse lenses, mild nuclear cataracts were observed along with disrupted actin cytoskeleton, cell shape and organization of equatorial epithelial cells, and misaligned and disorganized fiber cells." (PMID 34899394, 2021).
Age-related cortical cataract (6 papers, 2008 to 2022). A type of age-related cataract that primarily affects the cortex of the lens. "In this study we found that single-nucleotide polymorphisms (SNPs) rs477558 and rs7548209 in EPHA2 were associated with age-related cortical cataract in a Han Chinese population." (PMID 21686326, 2011). "Recently, several EPHA2 variants were found to be associated with age-related cortical cataracts in different worldwide Caucasian populations." (PMID 21686326, 2011). "In addition, genetic variants of the EPHA2 gene were identified to confer risks for age-related cortical cataracts in a Caucasian population." (PMID 21686326, 2011). "A patient from family OFT-00463 had a variant in EPHA2 (OMIM:176946), a gene related to age-related cortical cataracts." (PMID 35457050, 2022).